IL10 (interleukin 10)
Diseases named in the same sentence as IL10 in open-access papers (continued):
Sharing a sentence is not in itself a finding about the gene and the disease.
tumor (continued). "Increased tumor infiltration with PD-1high IL-10-producing Bregs was associated with reduced number and dysfunction of CD8+ cells." (PMID 27437104, 2016). "There is also some evidence of solid malignancies causing immune dysregulation via tumor-derived soluble factors such as IL-10 and TGF-beta." (PMID 27529042, 2016). "Tumor-associated O-glycans induce a tolerogenic programming of tumor-resident DCs, characterized with low expression of co-stimulatory molecules, high IL-10 secretion and an incapacity to induce of effector T cell responses." (PMID 27153100, 2016). "It must however be noted that expression of CD200 is thought to have links to anti-tumor effects by inhibiting activity of tumor-associated myeloid cells via IL-10, arguing caution in targeting a molecule with potentially pleiotropic effects." (PMID 27462861, 2016). "This unique cytokine signature has been shown to promote tumor metastases, and circulating levels of IL-10 were reported to be associated with poor prognosis." (PMID 27239288, 2016). "Some mechanisms responsible for dysfunction of immune cells are directly mediated by factors produced by tumors, whereas others result from tumor-associated microenvironment, including IL-1β, IL-4, IL-6, IL-10, IFN-γ and TGF-β." (PMID 27391078, 2016). "As tumors become increasingly aggressive, tumor-associated macrophages express high levels of immunosuppressive cytokines, such as IL-10 and TGFβ." (PMID 26106384, 2015). "Tumor-derived factors like IL10, IL6, CSF1, and VEGF interfere with DC maturation, causing failure to migrate to the tumor-draining lymphoid organs, and to provide the appropriate co-stimulatory signals required to stimulate T cells." (PMID 26500653, 2015). "MDSCs are also known to secrete numerous immunosuppressive cytokines, and M2-polarized tumor-associated macrophages are even defined by their ability to express IL-10, so the abundance of these cytokines in the tumor microenvironment is unsurprising." (PMID 25941795, 2015). "Apart from TGF-β and IL-10, expression of the Treg-associated cytokine IL-35 has been demonstrated in the tumor environment." (PMID 25682197, 2015). "It was concluded that IL-10 ablation promotes tumor development, growth and metastasis as tumor growth in IL-10 knock out mice was associated with an increased level of MDSCs and Tregs in both the tumor environment and in the tumor-draining lymph nodes." (PMID 25682197, 2015). "The majority of tumour-associated macrophages are alternatively activated, as they promote tumour angiogenesis and tissue remodelling and their major product, IL-10, has known immunosuppressive roles." (PMID 26040322, 2015). "Despite upregulation of typical M2 markers (arginase I and IL-10), usually associated with tumor progression, SOCS3-deficient macrophages provided tumor protection because of enhanced MCP-2/CCL8 production." (PMID 26579124, 2015). "Progression of tumor is associated with an increase in Treg cell population which secrete immunosuppressive cytokines like TGFβ and IL10." (PMID 26464579, 2015). "IL-10+ Breg deficiency can enhance anti-tumor action, while Bregs evoked by tumor cells (tBregs) inhibit anti-tumor responses and upregulate Tregs, thus facilitating breast cancer metastasis." (PMID 26378021, 2015). "In EOC, an impaired anti-tumor immune response seems to be associated with increased IL-10 levels, also reflected in higher levels in high grade compared to low grade tumors." (PMID 26457674, 2015). "CCL2, CCL22, TGF-β and IL-10 augment the differentiation of M2-like tumor-associated macrophages (TAMs) and recruitment of immunosuppressors including TAMs, MDSCs and Tregs." (PMID 26683520, 2015). "Ligation of DC-SIGN and tumor-associated Le glycans also strongly enhance LPS-induced anti-inflammatory cytokine secretions of IL-6 and IL-10 by monocyte-derived DCs." (PMID 26379663, 2015).
tumor (continued). "Conversely, M2 macrophages release immunosuppressive cytokines such as interleukin-10 and allow tumor progression; hence they are called tumor-associated macrophages (TAMs)." (PMID 26075202, 2015). "Numerous studies show that increase in IL-10 produced by macrophages is associated with tumor progression, while other studies suggest that IL-10 plays a positive role in tumor rejection." (PMID 24633175, 2014). "Other factors secreted by HNSCC tumors, including monocyte chemotactic protein 1 (MCP-1), have been shown to contribute to immunosuppression at the tumor site by recruiting a population of IL-10 and TGF-β-secreting M2 skewed tumor-associated macrophages." (PMID 24698959, 2014). "They reduce anti-tumor immunity by suppressing NK cell cytotoxicity, and IL-10 and IL-6 have been implicated in DC dysfunction." (PMID 24917865, 2014). "Mast cell activation by complement C5a will cause CCL2 and CCL5 upregulation, which has been to shown to induce Tumor Associated Macrophages (TAMs) to release IL-10, promote angiogenesis, and stimulate tumor metastasis." (PMID 24949488, 2014). "Tumor-induced inflammation causing secretion of serum amyloid A1 (SAA-1) induced differentiation of suppressive IL-10-producing neutrophils." (PMID 25389427, 2014). "IL-4 polarizes myeloid precursors towards a M2 phenotype, which is strongly associated with tumor associated MDSCs and express IL-10 to mediate their immune suppressive effects." (PMID 24733360, 2014). "Haptenation will also cause keratinocytes to release IL-1β, IL-6, IL-18, and TNFα, which have been shown to cause MDSC recruitment and infiltration at the tumor site, subsequently causing IL-10 release and immune suppression." (PMID 24949488, 2014). "In vivo, macrophage polarization induced by IL-10 is associated with the production of this cytokine in infected organs and tumor microenvironment." (PMID 25419575, 2014). "Potential drugs that directly inhibit STAT3 activation include the naturally occurring triterpenoid oleanolic acid, which also suppresses the M2 polarization of tumor-associated macrophages by suppressing IL-10 secretion." (PMID 24518612, 2014). "The STAT3 pathway is more highly activated in response to several cytokines, including IL-1β, IL-4 and IL-10 in tumor-associated macrophages of the M2 phenotype than in M1 macrophages." (PMID 25198511, 2014). "We have recently demonstrated that tumor-associated Treg secrete high amounts of IL-10, which in turn impairs DC migration to the draining lymph nodes and the mounting of a specific anti-tumor immune response." (PMID 23986759, 2013). "A growing number of studies indicates the unique ability of tumor-associated IL-10 to convert even fully differentiated DC to CD14+ suppressive macrophage-like cells." (PMID 24324467, 2013). "Our main aim was to identify a protocol able to consistently provide 100% tumor protection, and this aim was achieved only when the most efficacious effector strategy was associated with IL-10 blockade to counteract Treg activity." (PMID 23663506, 2013). "Non-soluble mediators expressed on colorectal carcinoma cells can contribute to this process as well, as IL-10 production by DC was increased following engagement of DC-SIGN by tumor-associated cell surface glycans." (PMID 23874338, 2013). "DCs in MM patients are a target of tumor-associated suppressive factors, such as IL-10, TGF-β, VEGF, and IL-6, resulting in their aberrant functions and impaired development of effector functions in tumor-specific lymphocytes." (PMID 22481968, 2012). "The association between IL-10 and tumor progression has frequently been explained by changes in immune suppression and tumor immune surveillance." (PMID 22848356, 2012). "In the tumor microenvironment, DC differentiation and function were suppressed by tumor-associated factors IL-10, VEGF, and TGFβ, resulting in immature/dysfunctional DC." (PMID 22481922, 2012).
tumor (continued). "Tumor-associated macrophages were described to have M2 properties, with low inflammatory chemokine receptors, poor antigen presentation, high IL-10, and low IL-12 production." (PMID 22494514, 2012). "A wide range of cell types is known to produce IL-10, as for example macrophages [in particular tumor-associated macrophages (TAMs)], B cells, T cells (especially Tregs), and epithelial cells." (PMID 22855687, 2012). "We demonstrate that adjuvant causes M2 polarized macrophages in the tumor to secrete the immune suppressive cytokine IL-10, and that that polarization of macrophages by dying cancer cells occurs through a transcriptional switch via regulation of NFκB p50." (PMID 22761754, 2012). "IFN-γ has antiviral, immunoregulatory and anti-tumor properties and is associated with Th1 responses while IL-10 is an anti-inflammatory cytokine associated with Th2 responses." (PMID 23144852, 2012). "IL-10 in combination with IL-6 can lead to upregulation of molecules in TAMs, which are implicated in suppression of tumour-specific T cell immunity." (PMID 22778767, 2012). "Impaired anti-tumor immune responses have also been associated with increased levels of IL-10 and TGF-β1 in many cancer patients." (PMID 22674057, 2012). "It has been reported that UV has been implicated in inhibition of anti-tumor T-cell immune response through elevated interleukin 10 (IL-10) and other cytokines level." (PMID 22639094, 2012). "This was recently demonstrated in vitro for the humanized Fc region optimized antibody cetuximab that binds the EGF-Receptor at the tumor cell surface and which caused activated M2 macrophages to produce IL-10 following the cross-linking of Fc-receptors." (PMID 22176642, 2011). "For example, in the HPV16 E6- and E7-expressing TC-1 tumor mouse model, TAMs were shown to cause suppression of the antitumor T-cell response, while their secreted IL-10 cytokine subsequently induced a regulatory T cell phenotype." (PMID 22190971, 2011). "These tumor cells secret IL-10, which can promote tumor growth and cause systemic immunosuppression." (PMID 21269511, 2011). "Tumor-associated macrophages (TAMs) share properties with M2 macrophages, including high expression of IL10 and mannose receptor (CD206), and low expression of IL-12." (PMID 22163010, 2011). "In human ovarian cancer, tumor-associated regulatory T (Treg) cells trigger macrophages to produce IL-6 and IL-10, and these cytokines in turn stimulate APCs to express B7-H4 in an autocrine and/or paracrine manner." (PMID 22013483, 2011). "In contrast, IFN-γ, TNF-α, IL-5, IL-4, IL-2 and low amounts of IL-10 were produced upon stimulation with the tumor cell lines encoding the HPV16E7wt and HPV16E7V constructs." (PMID 21892941, 2011). "Prolonged survival and a decrease in tumor development were observed in other in vivo models using IL-10 deficient animals." (PMID 20525400, 2010). "In this study, we observed a decrease of tumor growth in mouse models where IL-10 signaling was blocked: IL-10 deficient mice or mice treated with anti-IL-10/anti-IL-10R neutralizing antibodies." (PMID 20525400, 2010). "Among them, the expression of suppressor cytokines like IL-10 has been described in many malignancies, including tumors and tumor precursor lesions associated to HPV." (PMID 20525400, 2010). "IL-24 (melanoma differentiation-associated gene-7 (mda-7)), a member of the IL-10 cytokine family, possesses the properties of a classical cytokine as well as tumor suppressor effects." (PMID 20072629, 2010). "In conclusion, TGF-β and IL-10 expression is intimately implicated in tumor development and contributes to many features of tumor cell biology." (PMID 20205946, 2010). "In this work, we sought to establish if IL-10 is part of the mechanism by which HPV tumor associated macrophages induce T cell regulatory phenotype, inhibiting anti-tumor activity and facilitating tumor growth." (PMID 20525400, 2010).
tumor (continued). "Tumor associated macrophages and myeloid derived suppressor cells express IL-10, among other cytokines, as part of the mechanism of suppression of T cell anti-tumor responses." (PMID 20525400, 2010). "We believe our work suggests that this is one of the possible mechanisms behind the epidemiologic data correlating HPV associated tumor progression and increase in IL-10 expression." (PMID 20525400, 2010). "Of note, tumor development in Il10−/− mice was associated with enhanced intestinal inflammation as determined by histological analysis (p<0.0001)." (PMID 19551144, 2009). "Genotyping for -1082 (G/A) includes three categories: GG is associated with high in vitro tumor IL-10 production, whereas AG and AA, are associated with intermediate and low production, respectively." (PMID 18221542, 2008). "An elevated preoperative C-reactive protein was associated with increased tumour stage, interleukin-6 and interleukin-10 concentrations." (PMID 17003778, 2006). "In summary, an elevated preoperative C-reactive protein was associated with increased tumour stage, interleukin-6 and interleukin-10 concentrations." (PMID 17003778, 2006). "In contrast to the beneficial effects of macrophages and dendritic cells on the tumor specific immune responses, tumor associated macrophages have been shown to secrete the immunosuppressive cytokine IL-10." (PMID 16164749, 2005). "How formation of such pathobiont‐dependent TLSs differs under conditions of IL‐10 deprivation versus tumor association may provide important insights into differences between pathogenic versus anti‐tumor functions of these structures." (PMID 41328802, 2026). "In addition, Tregs promote the polarization of macrophages into M2-type tumor-associated macrophages (M2-TAMs) by secreting IL-10 and TGF-β." (PMID 40008144, 2025). "In CRC, KRASG12C/D/V mutations resulted in ROS accumulation, leading to the upregulation of lactate and GM-CSF, thus recruiting macrophages and transforming them into more tumor-supportive tumor-associated macrophages (TAM)-like cells that secreted higher levels of IL-10, CCL17, and TGF-β1." (PMID 40611261, 2025). "In terms of immune activation, MSCs promote T cell infiltration into tumor sites, significantly restraining tumor growth—an effect potentially linked to high levels of anti-inflammatory cytokines such as IL-10 in the TME, inducing a pro-inflammatory phenotype in MSCs." (PMID 41301162, 2025). "In contrast, KC3 was enriched for transforming growth factor‐β (TGF‐β) tumor immune microenvironment and interleukin (IL)‐10 signalling pathways, both of which are associated with strong immune suppression, suggesting a stromal‒immune axis of immune suppression." (PMID 41025426, 2025). "Furthermore, greater amounts of IL-10 in the serum or tumor tissues have been linked to a reduced survival rate in patients with LC, highlighting the potential impact of IL-10 on cancer development." (PMID 41179937, 2025). "Tumor-associated macrophages (TAMs), myeloid-derived suppressor cells (MDSCs), and regulatory T cells (Tregs) secrete immunosuppressive cytokines, including IL-10 and TGF-β, that dampen anti-tumor immunity and enable immune evasion." (PMID 39936963, 2025). "However, tumor associated dendritic cells have been shown to exert immunosuppressive effects by secreting IL-10 and TGF-β1, and can promote tumor cell growth." (PMID 40050933, 2025). "It must be, however, underlined that both IL-10 and TNFα may have both a pro- and an anti-tumor properties with respect to gastric carcinogenesis and that, therefore, our findings should be cautiously considered." (PMID 40534691, 2025). "Elevated levels of IL-10 are typically observed in this environment, and this cytokine is linked to poorer survival rates because it promotes tumor growth by suppressing pro-inflammatory responses, including antigen presentation, T cell proliferation, Th1 cytokine production, and cytotoxicity." (PMID 41019059, 2025).
tumor (continued). "Additionally, exosomal circRNAs from macrophages, such as circMERTK, enhance IL-10 production in tumor-associated macrophages (TAMs), which suppresses CD8+ T-cell function and contributes to the immunosuppressive TME." (PMID 40291917, 2025). "On the other hand, butyrate (derived from Faecalibacterium, Roseburia, and Akkermansia) could modulate antitumor immunity by down-regulating IL-10 and programmed death ligand 1 (PD-L1) in tumor-associated macrophages, while enhancing CD8+ T-cell cytotoxicity." (PMID 40357361, 2025). "Other cytokines and molecules in the tumour microenvironment (e.g., IL‐10, TGFβ‐1 and PGE) also regulate tumour‐associated myeloid cells, as they play significant roles in the functional polarisation of monocytes/macrophages into an immunosuppressive phenotype." (PMID 40434054, 2025). "Indeed, aging is accompanied by greater central nervous system inflammation and increased immunosuppressive TGFβ and interleukin 10 (IL-10) factors that impair the immune system and can cause a tumor onset." (PMID 40647449, 2025). "Immunosuppressive cytokines including TGF-β and IL-10 are secreted by TME components like tumor-associated macrophages (TAMs), regulatory T cells (Tregs), and myeloid-derived suppressor cells (MDSCs), which inhibit the function and proliferation of CAR-T cells." (PMID 39755633, 2025). "However, at the same time, factors like TGF-β, IL-10 and tumor-associated cells like macrophages and macroglia reduce their immunological capacity by restricting T-cell activation." (PMID 41417285, 2025). "P. acnes significantly increases in GC tissues infected with H. pylori, activating the TLR4/PI3K/Akt signaling pathway, inducing polarization of M2-type tumor-associated macrophages (TAMs), and promoting the secretion of immunosuppressive factors IL-10 and CCR-2." (PMID 40529304, 2025). "In TAMs, canonical NF-κB (RelA/p50) promotes proinflammatory cytokine production (e.g., TNF-α, IL-6) in inflammation-driven cancers (e.g., colitis-associated colon cancer) or immunosuppressive IL-10 secretion in breast and ovarian cancers, fostering tumor growth and immune escape." (PMID 40562870, 2025). "Among these, IL-2 and TNF-α are especially relevant for T cell expansion and anti-tumor immunity, while IL-4 and IL-10, linked to Th2 responses, may play a lesser role in MM immune surveillance." (PMID 40948764, 2025). "Furthermore, cytokines and signaling molecules such as IL-33, IL-6, GM-CSF, IL-4, and IL-10 orchestrate histone modification patterns in tumor-infiltrating MDSCs and tumor-associated macrophages (TAMs), enhancing their immunosuppressive functions." (PMID 41301911, 2025). "Tumor-associated macrophages (TAMs) polarized to M2 phenotypes, regulatory T cells (Tregs), and MDSCs collectively establish an immunosuppressive milieu by secreting IL-10, TGF-β, and other cytokines that inhibit cytotoxic T cell function." (PMID 41364140, 2025). "IL-10 can induce the pro-angiogenic M2 polarization of tumor-associated macrophages (TAMs)." (PMID 40977714, 2025). "For example, tumor-associated macrophages (TAMs) exhibit different polarization states within LC organoids, where M2-type TAMs promote tumor cell proliferation and metastasis by secreting cytokines, name a interleukin 10 (IL-10)." (PMID 41359105, 2025). "Several studies have provided evidence that deficient IL-10 signaling promotes tumor development." (PMID 38543305, 2024). "However, tumor-associated macrophages (TAMs) always act as promoters of tumor progression by secreting anti-inflammatory cytokines such as IL-10 and TGF-β." (PMID 38705987, 2024). "Additionally, HIF-2α is associated with diminished tumor-infiltrating lymphocytes and enhanced immunosuppressive IL-10 and TGF-β signaling." (PMID 38339352, 2024).